HECTD3 (HECT domain E3 ubiquitin protein ligase 3)
Description:
E3 ubiquitin ligases accepts ubiquitin from an E2 ubiquitin-conjugating enzyme in the form of a thioester and then directly transfers the ubiquitin to targeted substrates. Mediates ubiquitination of TRIOBP and its subsequent proteasomal degradation, thus facilitating cell cycle progression by regulating the turn-over of TRIOBP. Mediates also ubiquitination of STX8 (By similarity).
Synonyms: FLJ21156
Tractability: PROTAC: ubiquitination databases record sites on it; its protein half-life has been measured.
Gene: Protein-coding gene on chromosome 1 (45,002,540 to 45,011,369, reverse strand). Ensembl gene ENSG00000126107.
Subcellular location: Cytoplasm, perinuclear region
Pathways (Reactome):
Immune System: Antigen processing: Ubiquitination & Proteasome degradation
Gene Ontology:
Molecular function: protein binding; ubiquitin-protein transferase activity; ubiquitin protein ligase activity
Biological process: proteasome-mediated ubiquitin-dependent protein catabolic process; protein ubiquitination
Cellular component: perinuclear region of cytoplasm
Genetic constraint (gnomAD): Loss-of-function variants: 72 observed, 105.86 expected, observed/expected ratio (o/e) 0.68, 90% interval 0.56 to 0.83. The upper end of that interval is the gene's LOEUF score, 0.83, which puts it in group 3 of 6, group 1 being the genes least tolerant of losing a copy. Missense variants: 1,041 observed, 1,124.2 expected, observed/expected ratio (o/e) 0.93, 90% interval 0.88 to 0.98. Synonymous variants: 481 observed, 446.26 expected, observed/expected ratio (o/e) 1.08, 90% interval 1 to 1.16.
Homologues: Orthologues: chimpanzee HECTD3 (99% identical), macaque HECTD3 (99% identical), rabbit HECTD3 (99% identical), pig HECTD3 (98% identical), dog HECTD3 (98% identical), rat Hectd3 (98% identical), mouse Hectd3 (98% identical), guinea pig HECTD3 (97% identical), zebrafish hectd3 (69% identical), tropical clawed frog hectd3 (68% identical).
Diseases named in the same sentence as HECTD3 in open-access papers:
HECTD3 is named in the same sentence as 32 diseases in open-access papers, as found by Europe PMC text mining. Sharing a sentence is not in itself a finding about the gene and the disease. The quoted sentences say what the papers report.
breast carcinoma (8 papers, 2018 to 2025). "To determine the role of Hectd3 in tumor metastasis, we analyzed metastasis susceptibility in Hectd3-deficient mice utilizing two malignant mouse breast cancer metastasis models after surgery." (PMID 35918322, 2022). "A previous study found that HECTD3 promoted breast cancer cell survival and may be a potential diagnostic and prognostic biomarker for breast cancer." (PMID 40839607, 2025). "HECTD3 is an oncogene and could promote breast cancer cell survival, which is in line with the result of our study that HECTD3 is a risk factor for TNBC." (PMID 36685836, 2022). "In human breast cancer, high expression levels of KRT10, HECTD3, NSD3, and STOML2 were associated with unfavorable outcomes, whereas high BTN1A1 expression was linked to a better prognosis." (PMID 40839607, 2025). "Specifically, HECTD3 exhibits an approximately twofold higher expression in breast cancer cell lines than normal mammary gland tissues." (PMID 40839607, 2025). "While, other phosphoproteins (e.g., BTN1A1, KRT10, HECTD3, NSD3, and STOML2) were associated with human breast cancer prognosis." (PMID 40839607, 2025). "HECTD3 is highly expressed in multiple cancers, including breast cancer, gastric cancer, ovarian cancer, and glioma." (PMID 39487119, 2024). "Other studies have reported that miR-153 promotes breast cancer cell apoptosis by targeting HECTD3 and suppresses human laryngeal squamous cell carcinoma migration by targeting the SNAI1 gene." (PMID 37381058, 2023). "It has been shown that miR-153 induces apoptosis through targeting HECTD3 in BT-549 breast cancer cells, whereas in another report miR-153 inhibits apoptosis through indirect targeting of caspase 3/7 activity in triple negative breast cancer." (PMID 36158686, 2022). "To this end, we firstly generated HECTD3 KO breast cancer cell lines using the CRISPR-Cas9 system." (PMID 39487119, 2024). "HECTD3 promotes ubiquitination of some types of caspases, including caspase 8 and 9, resulting in apoptosis inhibition and cell survival promotion in cancer cells such as breast cancer." (PMID 36158686, 2022). "These suggested that HECTD3, PSMB10, UBD, UBE2C, and UBE2S might also affect the efficacy of neoadjuvant chemotherapy in breast cancer through the ubiquitin proteasome pathway." (PMID 29685151, 2018). "Besides, HECTD3, PSMB10, UBD, UBE2C, and UBE2S involved in the ubiquitin proteasome pathway, as well as CCL2, CCR1, CXCL10, CXCL11, and IL2RG implicated in the cytokine–cytokine receptor interaction pathway, might be used for evaluating the efficacy of neoadjuvant chemotherapy in breast cancer." (PMID 29685151, 2018). "Although there has been no research to date on the role of HECTD4 in breast cancer, relevant studies have suggested that other similar genes in the HECT family, such as HECTD1 and HECTD3, play significant roles in breast cancer progression and treatment response." (PMID 41168812, 2025).
experimental autoimmune encephalomyelitis (2 papers, 2019 to 2024). An autoimmune demyelinating disease of the central nervous system that is produced experimentally in animals by the injection of homogenized brain or spinal cord in Freund's adjuvant. "Here we show that the E3 ubiquitin ligase Hectd3 is necessary for pathogenic Th17 cell generation in experimental autoimmune encephalomyelitis (EAE), a mouse model for human multiple sclerosis." (PMID 30741923, 2019). "HECTD3 plays important roles in experimental autoimmune encephalomyelitis, bacterial infection and inflammation-related tumor metastasis." (PMID 38267403, 2024).
gastric cancer (2 papers, 2022 to 2024). A primary or metastatic malignant neoplasm involving the stomach. "HECTD3 inhibits apoptosis in gastric cancer cells by polyubiquitinating c-Myc with K29 linked polyubiquitin chains." (PMID 39487119, 2024). "Our experimental results reveal that HECTD3 facilitates the malignant proliferation of gastric cancer by mediating K29 site-linked polyubiquitination of c-MYC." (PMID 35397617, 2022). "Depletion of HECTD3 restrained the proliferative and clone abilities of cells and induced the apoptosis of gastric cancer cells." (PMID 35397617, 2022). "The database analysis indicated that expression of HECTD3 gradually with increasing age in gastric cancer patients." (PMID 35397617, 2022). "The results indicated that depletion of HECTD3 clearly restrained the multiplication ability of gastric cancer cells." (PMID 35397617, 2022). "Here, we discovered that HECTD3 is abnormally activated in gastric cancer, and the clinical prognosis database suggested that HECTD3 was strongly expressed in gastric cancer." (PMID 35397617, 2022). "In general, these results revealed that the abnormal activation of HECTD3 in gastric cancer and participates in cell cycle and apoptosis." (PMID 35397617, 2022). "Western blot and MTT experiments were used to determine proliferation of HECTD3-overexpressing HECTD3-knockdown gastric cancer cells." (PMID 35397617, 2022). "Our results revealed abnormal activation of HECTD3 in gastric cancer cells, and depletion of HECTD3 restrains the proliferative ability of cells and induces apoptosis." (PMID 35397617, 2022). "Next, the prognosis of HECTD3 in gastric cancer was analyzed through the R2 prognosis database and Kaplan–Meier plotter." (PMID 35397617, 2022). "These assay data suggested that the study of HECTD3 in gastric cancer warrants further attention." (PMID 35397617, 2022). "The study indicated that HECTD3 is abnormally activated gastric cancer cells." (PMID 35397617, 2022). "Then, BrdU experiments were adopted to determine the levels of DNA synthesis in response to overexpression of HECTD3 in HECTD3 knock down gastric cancer cells, and the experiments revealed that levels of DNA synthesis were significantly rescued compared to that in the control groups." (PMID 35397617, 2022). "Our study primarily explored the important function and effects of HECTD3 in gastric cancer." (PMID 35397617, 2022). "Our experimental data suggested that HECTD3 is essential for gastric cancer cell multiplication." (PMID 35397617, 2022). "In our assay, we explored the function and role of HECTD3 in gastric cancer." (PMID 35397617, 2022). "Our study indicated that HECTD3 is essential for gastric cancer cell multiplication." (PMID 35397617, 2022). "Next, a proximity ligation (PLA) experiment was employed to observe the interaction of HECTD3 and c-MYC in gastric cancer cells." (PMID 35397617, 2022). "However, biological effect of HECTD3 in gastric cancer is unknown." (PMID 35397617, 2022). "Our assay results discovered that the mRNA levels of c-MYC was no markedly change in knockdown HECTD3 gastric cancer cells." (PMID 35397617, 2022). "Then, the Protein Atlas database was performed to check the positive rate of HECTD3 in human nontumor gastric mucosa and gastric cancer." (PMID 35397617, 2022). "Subsequently, HECTD3 expression was examined in GES-1 noncancerous gastric mucosa cells and gastric cancer cell lines through western blot." (PMID 35397617, 2022).
glioma (2 papers, 2023 to 2024). A benign or malignant brain and spinal cord tumor that arises from glial cells (astrocytes, oligodendrocytes, ependymal cells). "Depletion of HECTD3 sensitizes glioma cells to radiation by regulating LKB1 ubiquitination and downregulating ZEB1 expression." (PMID 39487119, 2024). "Interestingly, HECTD3 mediated LKB1 ubiquitination promotes radiation resistance in glioma." (PMID 39487119, 2024).
triple-negative breast carcinoma (2 papers, 2018 to 2024). An invasive breast carcinoma which is negative for expression of estrogen receptor (ER), progesterone receptor (PR), and human epidermal growth factor receptor 2 (HER2). "Through regulating HECTD3, miR-153 suppresses the survival of the patients with triple-negative breast cancer (TNBC) and acts as a potential tumour suppressor." (PMID 29685151, 2018).
breast tumor (1 paper, 2022). "When we replaced inflammation factor LPS with TNFα, Hectd3 KO also significantly inhibited lung colonization of 4T1-Luc2 breast tumor cells." (PMID 35918322, 2022). "To address this question, we conducted in vivo tumor cell adhesion assays by injecting GFP-labeled PyMT-induced mouse breast tumor cells into WT or Hectd3−/− mice through the tail vein." (PMID 35918322, 2022).
cardiac hypertrophy (1 paper, 2020). "Consistent with the in vitro findings, overexpression of HectD3 in mouse hearts inhibited cardiac hypertrophy and moderately improved cardiac function compared to control AAV-injected mice after TAC." (PMID 33037313, 2020). "The beneficial effects exerted by AAV-mediated overexpression of HectD3 reveal a translational perspective and support further exploration of its therapeutic potential in cardiac hypertrophy and inflammation." (PMID 33037313, 2020). "We thus propose HectD3 as a “dual pathway” inhibitor for the prevention and/or therapy of cardiac hypertrophy and heart failure, e.g. utilizing AAV-mediated gene transfer." (PMID 33037313, 2020). "Notably, our findings suggest that HectD3-overexpression in cardiomyocytes could significantly attenuate the accumulation of macrophages in the two investigated in vivo models of cardiac hypertrophy and heart failure." (PMID 33037313, 2020).
Chronic pain (1 paper, 2025). Persistent pain, usually defined as pain that has lasted longer than 3 to 6 months. "Among the 42 new chronic pain loci that harbor protein-coding variants, five genes (HECTD3 (chr1.p34.3), CCDC17 (chr1.p34.3), DNM1 (chr9.q33.1), PCDHA1 (chr5.q31.5), and WDR90 (chr16.p13.3)) showed evidence of colocalization in more than one brain tissue." (PMID 40297705, 2025).
Cognitive impairment (1 paper, 2024). Abnormal cognition is characterized by deficits in thinking, reasoning, or remembering. "HECTD3 promotes NLRP3 inflammasome and pyroptosis, thereby exacerbating diabetes-related cognitive impairment by stabilizing MALT1 and regulating the JNK pathway." (PMID 38384936, 2024).
colon cancer (1 paper, 2024). "We then used the Ualcan dataset to select four candidate E3 ligases (TRIM25, HECTD3, NEDD4L, WWP2) whose mRNA levels were lower in colon cancer tissue samples compared to normal colon tissues." (PMID 38803048, 2024).
colorectal cancer (1 paper, 2024). A primary or metastatic malignant neoplasm that affects the colon or rectum. "On the contrary, a recent study reported that homologous to the E6-associated protein carboxyl terminus domain containing 3 (HECTD3) promoted xCT degradation and stability via poly-ubiquitination manner, thereby triggering ferroptosis and suppressing tumor growth in colorectal cancer (CRC)." (PMID 39557844, 2024).
esophageal squamous cell carcinoma (1 paper, 2024). Esophageal squamous cell carcinoma (ESCC) is a type of esophageal carcinoma (EC) that can affect any part of the esophagus, but is usually located in the upper or middle third. "HECTD3 promotes esophageal squamous cell carcinoma (ESCC) growth and cell survival by suppressing Caspase-9 activation." (PMID 39487119, 2024).
glioblastoma (1 paper, 2024). The most malignant astrocytic tumor (WHO grade IV). "Similarly, HECTD3-mediated K63-linked polyubiquitination of PARP1 results in DNA lesions in glioblastoma cells, increasing apoptosis vulnerability." (PMID 39528473, 2024).
gouty arthritis (1 paper, 2024). "Subsequently, we found that Hectd3 deficiency in myeloid cells could promote MSU-induced gouty arthritis." (PMID 38267403, 2024). "We demonstrate that HECTD3 inhibits gouty arthritis, a NLRP3-related inflammatory disease by inhibiting assembly and activation of the NLRP3 inflammasome." (PMID 38267403, 2024). "This study demonstrates that HECTD3 plays a critical role in MSU-induced gouty arthritis, a NLRP3-related diseases and suggests potential therapeutic strategies for NLRP3-related inflammatory diseases by targeting the HECTD3-NLRP3 interaction." (PMID 38267403, 2024). "Collectively, these findings showed that HECTD3 in myeloid cells reduced MSU-induced gouty arthritis, a NLRP3-dependent disease via suppressing the activation of the NLRP3 inflammasome." (PMID 38267403, 2024). "Furthermore, HECTD3 inhibits monosodium urate crystals (MSU)-induced gouty arthritis, a NLRP3-related disease." (PMID 38267403, 2024).
hypertrophic cardiomyopathy (1 paper, 2020). A condition in which the myocardium is hypertrophied without an obvious cause. "Interestingly, an inverse correlation of expression levels of SUMO2 and HectD3 was observed in human heart samples from hypertrophic cardiomyopathy patients." (PMID 33037313, 2020).
multiple sclerosis (1 paper, 2019). A progressive autoimmune disorder affecting the central nervous system resulting in demyelination. "Here the authors show that an ubiquitination enzyme, Hectd3, ubiquitinates Stat3 and Malt1 to modulate their function but not degradation in T cells, and thereby promoting the differentiation of pathogenic Th17 cells and susceptibility to a mouse model of multiple sclerosis." (PMID 30741923, 2019).
psoriasis (1 paper, 2019). An autoimmune condition characterized by red, well-delineated plaques with silvery scales that are usually on the extensor surfaces and scalp. "Therefore, Hectd3 may be a favorable target for MS, other Th17-related diseases such as psoriasis, or cancer therapy since Stat3 activation is instrumental in their pathogenesis." (PMID 30741923, 2019).
Tourette syndrome (1 paper, 2022). A neurologic disorder caused by defective metabolism of the neurotransmitters in the brain. "Interestingly, the HECTD3 mutant (R478C), which has been linked to Tourette syndrome, lies i-3 from the conserved phenylalanine of the α1′-helical extension that protects the hydrophobic pocket." (PMID 36111624, 2022).
virus infection (1 paper, 2023). "This suggests that HECTD3 can promote the proinflammatory effect of PKR at the early stage of virus infection and thus alert surround cells." (PMID 37402711, 2023). "Our findings add mechanistic insight to the understanding of HECTD3 in promotion of viral replication and virus-induced inflammation, and also propose a potential target to be pharmacologically inhibited for suppressing viral infection and innate inflammation." (PMID 37402711, 2023).
cancer (11 papers, 2017 to 2026). A tumor composed of atypical neoplastic, often pleomorphic cells that invade other tissues. "IKKα overexpression promoted the attachment of cancer cells to monolayer-cultured HUVECs and largely rescued the reduction of adhesion phenotype caused by HECTD3 KD." (PMID 35918322, 2022). "Thus, modulating HECTD3 is implicated in miR-153-induced apoptosis in these cancer cells." (PMID 36158686, 2022). "HECTD3, a member of the "other HECT" family, is implicated in the regulation of inflammation, apoptosis, and infection and highly expressed in several cancers." (PMID 41690955, 2026). "Recently, we demonstrated that HECTD3 promotes cancer metastasis by ubiquitinating IKKα and increasing kinase activity in endothelial cells." (PMID 39487119, 2024). "HECTD3 ubiquitinates p62 at K420 via K63 and K29 linked polyubiquitin chains and promotes autophagy and DSB repair, and its genetic ablation or pharmacological inhibition has shown to be a promising strategy to increase radiosensitivity of cancer cells." (PMID 39487119, 2024). "Taken together, the HECTD3-IKKα axis may serve as an effective prevention target for inflammation-induced cancer metastasis." (PMID 35918322, 2022). "In general, based on the abnormal expression of HECTD3 in a variety of tumors, HECTD3 may represent a powerful target for a variety of cancer treatments and bringing much needed relief to human tumor patients." (PMID 35397617, 2022). "Likewise, knockdown of HECTD3 or p65 significantly inhibited attachment of cancer cells to monolayer-cultured HUVECs." (PMID 35918322, 2022). "Furthermore, proteins, such as butyrophilin subfamily 1 member A1, keratin, type I cytoskeletal 10, HECT domain E3 ubiquitin protein ligase 3, nuclear receptor binding SET domain protein 3, and stomatin-like 2, were identified and implicated in cancer progression and prognosis." (PMID 40839607, 2025). "HECTD3, a member of the third subfamilies of HECT ligases, was validated to target and ubiquitinate caspase-9, c-MYC, and TRAF3 in cancers, already." (PMID 37031183, 2023). "Consistently, overexpression of WT HECTD3 but not HECTD3 C823A mutant in HUVECs significantly increased the adhesion of cancer cells to LPS-treated HUVECs." (PMID 35918322, 2022).